GARIN5B (golgi associated RAB2 interactor family member 5B)
Synonyms: C19orf16; FAM71E2; DKFZp434G1729
Tractability: No criterion of Open Targets' tractability assessment is met for any kind of drug.
Gene: Protein-coding gene on chromosome 19 (55,354,908 to 55,363,260, reverse strand). Ensembl gene ENSG00000180043.
Genetic constraint (gnomAD): Loss-of-function variants: 75 observed, 77.2 expected, observed/expected ratio (o/e) 0.97, 90% interval 0.81 to 1.18. The upper end of that interval is the gene's LOEUF score, 1.18, which puts it in group 5 of 6, group 1 being the genes least tolerant of losing a copy. Missense variants: 1,220 observed, 1,183.4 expected, observed/expected ratio (o/e) 1.03, 90% interval 0.98 to 1.08. Synonymous variants: 481 observed, 516.09 expected, observed/expected ratio (o/e) 0.93, 90% interval 0.86 to 1.
Homologues: Orthologues: chimpanzee GARIN5B (95% identical), macaque GARIN5B (81% identical), pig GARIN5B (54% identical), dog GARIN5B (49% identical), rat Garin5b (39% identical), mouse Garin5b (36% identical). Paralogues in human: GARIN3 (15% identical), GARIN4 (13% identical), GARIN2 (9% identical), GARIN1B (8% identical), GARIN5A (7% identical), GARIN1A (7% identical), GARIN6 (7% identical).
Diseases named in the same sentence as GARIN5B in open-access papers:
GARIN5B is named in the same sentence as 1 disease in open-access papers, as found by Europe PMC text mining. Sharing a sentence is not in itself a finding about the gene and the disease.
GARIN5B shares sentences with these, for which no sentence is quoted: Obesity (1 paper).